TIGIT (T cell immunoreceptor with Ig and ITIM domains)
Diseases named in the same sentence as TIGIT in open-access papers (continued):
Sharing a sentence is not in itself a finding about the gene and the disease.
cancer (continued). "TIGIT can restrict the proliferation of T cells, inhibit the activation of T cells and NK cells, and block multiple steps of the cancer immune cycle." (PMID 36756040, 2023). "In cancer patients and mice, high TIGIT expression in Tregs was correlated with effective antibody-dependent killing and preferential depletion of the immunosuppressive Treg population." (PMID 36765704, 2023). "These recent developments highlight the promise of simultaneously targeting PD-1/PD-L1 and TIGIT or LAG-3 pathways for cancer immunotherapy." (PMID 37332070, 2023). "Accordingly, blockade of the TIGIT/CD155 axis has also emerged as a novel therapeutic strategy for various malignant tumours, including lung cancer." (PMID 38065981, 2023). "Several preclinical studies have supported the use of TIGIT blockade for the treatment of some advanced malignant tumors." (PMID 37064147, 2023). "Through our pan-cancer analysis, we found that CEP55 was significantly correlated with MDSCs and Th1 cells in most cancers and positively correlated with the expression of checkpoints, such as PD1, CTLA4, LAG3, and TIGIT in certain cancer types." (PMID 37484531, 2023). "We analyzed the expression profile of COMMD2 gene and ICGs (CD274, CTLA4, HAVCR2, LAG3, PDCD1, PDCD1LG2, SIGLEC15, and TIGIT) at a pan‐cancer level." (PMID 36205192, 2023). "In certain types of cancer such as follicular lymphoma, TIGIT is strongly expressed by intratumoral Tregs as well as memory CD8+ T cells." (PMID 36874131, 2023). "The strongest interaction we observed between CD8 + T cells and cancer cells was TIGIT-PVR, which significantly decreased with treatment." (PMID 36781852, 2023). "In response to the expression of TIGIT protein in cancer, a variety of therapeutic antibodies have been developed in phase I-II clinical trials." (PMID 37124530, 2023). "Overall, co-inhibition of TIGIT and PD-1/PD-L1 represents a promising therapeutic approach for cancer treatment that has the potential to improve the outcomes of cancer patients treated with ICIs." (PMID 37291608, 2023). "TIGIT is a T-cell receptor involved in limiting T-cell function and adaptive immune responses in the context of cancer immune evasion mechanisms." (PMID 37109579, 2023). "For example, in bladder cancer, TIGIT + Tregs accumulated around cancer tissues, promoted cancer cell metastasis and suppressed the antitumor immune response by promoting IL-32 expression in Tregs." (PMID 37670328, 2023). "The simultaneous use of PD‐1 and TIGIT now appears to be very promising because TIGIT inhibition or in combination with PD‐1 inhibition primarily works on NK cells to promote antitumor response and inhibit cancer progression." (PMID 36880420, 2023). "The expression of ICOS mediates infiltration of immune cells and is positive correlated with the expression of PDCD1, CTLA4, and TIGIT in most cancer types." (PMID 36855091, 2023). "The A2A receptor was additionally observed to be upregulated on the surface senescent cancer cells, which at the same time showed increased TIGIT expression following some chemotherapy regimens." (PMID 36874131, 2023). "Functionally, TIGIT has been demonstrated to be crucial in inducing immunosuppressive effects in cancer immunotherapy, like CTLA-4 and PD-1/PD-L1." (PMID 37291608, 2023). "In numerous cancers, TIGIT signaling negatively regulates antitumor immunity, and CD47 overexpression has been reported to be associated with poor survival and a higher rate of progression to AML in MDS patients." (PMID 36816361, 2023). "TIGIT-expressing Tregs are found at high levels in the microenvironment of various types of cancer, including CRC, and are believed to play a role in suppressing antitumor immune responses." (PMID 37835436, 2023). "TIGIT of O‐TPNVs bound to CD155 on the surface of cancer cells, blocked CD155–TIGIT signaling, and restored the activity of CD8+ T cells." (PMID 37409429, 2023).
cancer (continued). "The data we present would suggest that this model of TIGIT inhibition is likely to contribute to a small fraction of the immune cells in particular cancers." (PMID 37596248, 2023). "Antibodies targeting GITR and TIGIT are both being actively evaluated in various clinical trials for cancer." (PMID 38008725, 2023). "In contrast, when we tested a TIGIT antagonistic antibody on TSCs from the same set of cancers, we observed increased TCR signaling and activation in both cytotoxic and dysfunctional CD8 T cells, including in expanded clonotypes." (PMID 38008725, 2023). "The potential of TIGIT as a credible cancer immunotherapeutic target is being tested in multiple phase I and II clinical trials." (PMID 36829496, 2023). "We only detected three significant interactions between CD8 + T cells and cancer cells, with TIGIT-PVR being the strongest." (PMID 36781852, 2023). "TIGIT was an inhibitory receptor expressed by lymphocytes that played an important role in limiting the antitumor response process and the cancer-immune cycle." (PMID 36823639, 2023). "These advances are expected to expand the benefits of the anti-TIGIT and anti-PD-1/PD-L1 combination for cancer patients." (PMID 37291608, 2023). "TIGIT is an emerging immune checkpoint that inhibits immune cell responses at multiple steps of the cancer immunity cycle and constitutes a major target in cancer immunotherapy." (PMID 36993982, 2023). "Other immune checkpoint pathways, such as LAG-3 and TIGIT, are also being investigated as potential targets for cancer therapy." (PMID 37031434, 2023). "TIGIT, an inhibitory receptor expressed on lymphocytes, has recently been considered an important target for cancer immunotherapy." (PMID 36930687, 2023). "Based on these findings, TIGIT has become the subject of increased research as a target for cancer therapy, especially in combination with other ICIs, such as PD-1 inhibitors." (PMID 36874131, 2023). "TIGIT binding CD155 expressed by cancer cells results in impaired cytokine secretion by TIGIT+CD8+T cells, and their activation is inhibited." (PMID 37106742, 2023). "Most studies used NK cell lines or tested TIGIT blockade to reactivate exhausted cells obtained from cancer patients." (PMID 37345049, 2023). "We next examined the associations of TLR4 expression with 8 immune checkpoints (PD-L1, CTLA4, HAVCR2, LAG3, PDCD1, PDCD1LG2, SIGLEC15, and TIGIT), and TLR4 expression was widely associated with the 8 immune checkpoints in most cancer types." (PMID 37576399, 2023). "In human cancers, TIGIT gene expression was found to be upregulated in tumors and correlated with poor prognosis for KIRC, KIRP, LGG, and UVM cancers." (PMID 37928556, 2023). "This review provides a comprehensive summary of the roles of TIGIT in cancer immunity, the mechanisms of co-inhibition of TIGIT and PD-1/PD-L1, and the current clinical trials of this combination therapy." (PMID 37291608, 2023). "TIGIT can bridge innate and adaptive immunity and modulate immune responses in autoimmunity, malignancies, and infections." (PMID 35794399, 2023). "All together, these results highlight the importance of the CD155/TIGIT/CD96/DNAM-1 axis in cancer immune surveillance outcome." (PMID 37629138, 2023). "TIGIT directly interacts with Fap2, the outer membrane protein of FN, leading to inhibition of the cytotoxic activity of natural killer (NK) cells against cancer cells." (PMID 36960042, 2023). "We observe decreased ligand-receptor interactions in treated samples, particularly between TIGIT on CD8 + T cells and its receptor on cancer cells, and identify TIGIT as the major inhibitory checkpoint molecule of CD8 + T cells." (PMID 36781852, 2023). "Our results revealed that high LMS was positively associated with the expression of CTLA4, PDCD1, TIGIT and GZMB in the EC and pan-cancer cohorts." (PMID 35834061, 2022).
cancer (continued). "A star member of the VSIG family is VSIG9, also known as TIGIT, which has emerged as a promising cancer therapeutic target due to its apparent function in limiting antitumor T-cell and NK-cell responses." (PMID 36189222, 2022). "It confirmed that Nectin4 is a cancer-specific TIGIT ligand, and is the only member of the Nectin family that interacts with TIGIT alone." (PMID 35720417, 2022). "Immunotherapies targeting the TIGIT/PVR axis are now being actively explored in clinical trials in various cancer patients." (PMID 36377656, 2022). "TIGIT is an inhibitory IC expressed by resting T and NK cells, upregulated along with activation and often overexpressed in a variety of cancers." (PMID 36291830, 2022). "Based on these results, the clinical evaluation of TIGIT blockade has been started in various cancer types, as monotherapy or in combination with anti-PD1/anti-PD-L1 drugs." (PMID 36544779, 2022). "According to ClinicalTrials.gov, in 2022, 48 clinical trials have been launched, recruiting cancer patients to study the anti-TIGIT blockade in malignancies treatment." (PMID 36497240, 2022). "BAP1-mutant UMs display a suppressive TIME enriched for M2 polarized macrophages and T cells expressing checkpoint or “exhaustion” markers such as LAG3, TIM3, and TIGIT, similar to findings in other cancer types." (PMID 35954340, 2022). "Given the wide range of actions and presence in TME, TIGIT appears to be a promising therapeutic target in cancer treatment." (PMID 35328510, 2022). "TIGIT-Nectin4 interaction inhibits natural killer (NK) cell activity, which is a crucial element of the anti-cancer immune response." (PMID 35634292, 2022). "A study has shown that blockade of TIGIT in mice can enhance antitumor immunity in an NK-dependent manner, suggesting the therapeutic value of anti-TIGIT inhibitors in cancer." (PMID 36042469, 2022). "T cell immunoreceptor with immunoglobulin and ITIM domain (TIGIT) is another promising new target for cancer immunotherapy." (PMID 35053435, 2022). "TIGIT also mediates TIL function in other cancers, and clinical trials are ongoing to evaluate anti-TIGIT immunotherapies in combination with other checkpoint inhibitors." (PMID 36077772, 2022). "In cancer, TIGIT + PD1 + CD8 + cells were previously found to be upregulated and to present altered function." (PMID 35821240, 2022). "The key immune checkpoints (CD274, CTLA-4, HAVCR2, LAG3, PDCD1, PDCD1LG2, SIGLEC15, and TIGIT) also had a significant relationship with DTYMK expression in approximately 20 kinds of cancers, except in MESO, PCPG, and UCS." (PMID 36094557, 2022). "TIGIT is a novel prognostic biomarker and immunotherapeutic target for various solid cancers because of its activity in cancer immunity and tumorigenesis." (PMID 36211383, 2022). "In conclusion, TIGIT, as a new immune checkpoint, possesses great potential for cancer immunotherapy." (PMID 36189222, 2022). "TIGIT has been reported to contribute to immune evasion and to be correlated with poor prognosis in several cancers." (PMID 35053427, 2022). "Correspondingly, poliovirus receptor (PVR, CD155), one of the main ligands of TIGIT, is mainly expressed in various human malignant tumors and myeloid cells." (PMID 35433470, 2022). "The binding of CD155 or CD112 to TIGIT inhibits the T-cells effector activity and leads to cancer immune evasion." (PMID 36497240, 2022). "Preclinical studies have demonstrated that the TIGIT/PVR axis is an attractive cancer immunotherapy target owing to its roles in modulating CD8+ T cell and NK cell responses." (PMID 36377656, 2022). "There is strong evidence that TIGIT blockade has a direct effect in reversing T-cell dysfunction in cancer patients." (PMID 36189222, 2022). "Dual blockade of the PD-1 and TIGIT coinhibitory receptors on T cells shows promising early results in cancer patients." (PMID 35263569, 2022).
cancer (continued). "In models of cancers and chronic viral infection, blockade of TIGIT was correlated with enhanced CD8+ T-cell effector functions." (PMID 35844584, 2022). "Compugen also initiated a phase 1/2 study evaluating the triple combination of COM701, anti-PD-1 (nivolumab), and BMS-96820 (anti-TIGIT) in ovarian, endometrial, and select PVRL2high cancers." (PMID 35812451, 2022). "Afterward, we evaluated the link between DTYMK expression and key immune checkpoints (CD274, CTLA-4, HAVCR2, LAG3, PDCD1, PDCD1LG2, SIGLEC15, and TIGIT) expression levels in pan-cancer." (PMID 36094557, 2022). "For cancer immunotherapy, T-cell immunoglobulin and TIGIT, as well as CTLA-4, PD-1, T-cell immunoglobulin 3 and lymphocyte activation gene 3, are the most commonly targeted checkpoints." (PMID 35659630, 2022). "Specifically, the T cell immunoreceptor with immunoglobulin and ITIM domain (TIGIT) is a promising new target for cancer immunotherapy." (PMID 35057760, 2022). "T cell immunoreceptor with Ig and ITIM domains (TIGIT) interacts with poliovirus receptor (PVR) to contribute to cancer immune escape." (PMID 36544779, 2022). "Recent advances have also proposed a dual blockade of PD-1 and TIGIT as a more inspiring method for cancer immunotherapy than a single TIGIT blockade." (PMID 36189222, 2022). "TIGIT blockade as monotherapy or in combination with other inhibitor receptors or drugs is emerging in clinical trials in patients with cancer." (PMID 35656508, 2022). "TIM‐3 and TIGIT have been reported as marker molecules of T‐cell exhaustion in chronic viral infections and cancer models." (PMID 35634956, 2022). "TIGIT expression is detectable in a wide range of human cancers and is often tightly correlated with T cell transcripts (CD4 and CD8A)." (PMID 35812451, 2022). "TIGIT expression was also negatively correlated with activated dendritic cells and mast cells in most of the cancers included." (PMID 36211383, 2022). "In 29 of the 33 cancer types, TIGIT was correlated with the expression of at least one MMR-related gene." (PMID 36046244, 2022). "Numerous recent studies have highlighted that the TIGIT/CD155/DNAM-1 axis plays a crucial role in immune response in both cancer and autoimmunity." (PMID 36497240, 2022). "TIGIT and PD-1 are co-expressed in regulatory T-cells in various cancers; anti-TIGIT antibodies demonstrated synergistic effects with anti-PD-1/PD-L1 antibodies." (PMID 35743435, 2022). "Our results identify a population of circulating CD39+ memory conventional CD4 T cells expressing PD-1 and, for the most part, TIGIT and was present at higher proportions in cancer patients than in healthy individuals." (PMID 35954341, 2022). "TIGIT+ immune cells were also shown to play a role in cancer invasion and metastasis in esophageal carcinoma." (PMID 35656508, 2022). "We also demonstrated that anti-TIGIT Ab (clone 1G9) improved survival in septic mice with preexisting malignancy (unpublished observations), a situation characterized by immune activation and development of effector/memory T cells." (PMID 33682797, 2021). "TIGIT is an emerging target in cancer immunotherapy where its activation in T cells by its ligand CD155 or CD112 expressed by cancer cells inhibits T cell responses." (PMID 33718188, 2021). "The researchers also found that TIGIT-positive NK cells are mostly PD-1 negative, while T cells had double-positive expression, which indicated that TIGIT depressed the anti-cancer efficacy more specifically dependent on NK cells." (PMID 34439285, 2021). "In recent times, the novel co-inhibitory receptor T cell Ig and Immunoreceptor Tyrosine-based Inhibitory Motif, ITIM, domain (TIGIT) has displayed an important role in modulating immune responses in both autoimmunity mechanisms and cancer immune-escape." (PMID 33782477, 2021). "The potential of targeting TIGIT was shown using in-vivo mouse models for cancers and chronic viral infection." (PMID 34572463, 2021).
cancer (continued). "T-cell immunoreceptor with immunoglobulin (Ig) and ITIM domains (TIGIT) are recently emerging as a novel promising target in cancer immunotherapy." (PMID 33721026, 2021). "In tissue microarrays, the clinic pathological analysis indicated that TIGIT was highly expressed in cancer tissues than adjacent tissues, and it was notably related to the pathological stage." (PMID 34659197, 2021). "Red-A overcomes immuno-resistance of NSCLCs to NK cells by down-regulating CD155 expression, which shows the possibility of developing checkpoint inhibitors targeting TIGIT/CD155 signalling to overcome immuno-resistance of cancer cells." (PMID 33399495, 2021). "The bispecific antibody dual targeting CD47 and TIGIT has also been designed for cancer immunotherapy (WO2020259535)." (PMID 34068552, 2021). "Its main ligand CD155 is over-expressed in several types of cancer and hampers immune surveillance by interacting with TIGIT on these immune cells." (PMID 34367161, 2021). "Several clinical trials are currently evaluating the efficacy of anti-TIGIT mAbs in patients with different types of cancer." (PMID 33670993, 2021). "TIGIT was positively correlated with at least one DNMTs expression in 17 types cancers, TIGIT was negatively correlated with DNMTs expression in 5 cancer types." (PMID 34795387, 2021). "The potency of human anti-TIGIT blocking mAbs on CD8+T cells has been demonstrated in cancer patients." (PMID 33670993, 2021). "Here we review the current knowledge of the immunomodulatory activity of TIGIT in anti-cancer immunity and its potential as a target for cancer immune checkpoint therapy." (PMID 34367161, 2021). "TIGIT is a recently identified coinhibitory receptor that is upregulated in the setting of cancer and functionally contributes to the impairment of antitumor immunity." (PMID 34100383, 2021). "These properties of TIGIT enhance the immunosuppressive functions, partially contributing to immune escape of malignant tumors." (PMID 33680972, 2021). "Numerous clinical trials on TIGIT-blockade in cancer have recently been initiated, predominantly combination treatments." (PMID 34367161, 2021). "Increasing attention has been paid to PVR in cancer immunotherapy since the verification of its role as the shared ligand for the immune checkpoint TIGIT and CD96." (PMID 34068552, 2021). "Our findings will allow us to take the next step into a further functional investigation of TIGIT and clinical application of TIGIT blockade in specific cancers, providing new insights and options for the patients with cancers." (PMID 34795387, 2021). "We found that the expression level of GRWD1 was positively correlated with the expression levels of immune checkpoint-related genes (CD274, CTLA4, HAVCR2, LAG3, PDCD1, PDCD1LG2, SIGLEC15, and TIGIT) in most types of cancer, especially in STAD." (PMID 34616846, 2021). "TIGIT affects the prognosis of cancer patients by inhibiting the function of immune cells through a variety of mechanisms." (PMID 34888386, 2021). "Accumulating data from the immune monitoring of cancer patients have revealed that TIGIT expression is elevated in T and NK cells, and it often appears to be associated with advanced disease status and poor clinical outcomes." (PMID 33670993, 2021). "In this review, we summarize the current knowledge and identify the gaps in our current understanding of TIGIT’s roles in cancer immunity, and provide, based on these insights, recommendations for its positioning in cancer immunotherapy." (PMID 34367161, 2021). "TIGIT expression on T cells has been demonstrated on dysfunctional or exhausted T cells in chronic diseases including viral immunity and cancer." (PMID 33995373, 2021). "Antibodies targeting TIGIT/PVR pathway have achieved good clinical results in cancer treatment, as so far six TIGIT-targeting antibodies were under pre-clinical or clinical trials." (PMID 33557880, 2021).